ZFAS1 (ZNFX1 antisense RNA 1)
Diseases named in the same sentence as ZFAS1 in open-access papers (continued):
Sharing a sentence is not in itself a finding about the gene and the disease.
tumor (continued). "The expression level of ZFAS1 was detected by reverse-transcription quantitative polymerase chain reaction (RT-qPCR) assay on RNA samples extracted from different kinds of tumor tissues." (PMID 30544408, 2018). "ZFAS1 has been suggested to function as a tumor suppressor or promoter in regulating tumor cell proliferation, differentiation, apoptosis, and migration." (PMID 29678899, 2018). "Five of 8 studies examined the correlation between ZFAS1 expression and tumor size, and the pooled OR of 0.71 (95% CI: −4.27; P = .014) suggested that the upregulated expression of ZFAS1 was associated with tumor size (size ≤5 cm vs>5 cm)." (PMID 30544408, 2018). "Recently, more and more studies conformably reported that ZFAS1 was overexpressed in most types of human cancers, and promoted tumor cell growth and metastasis." (PMID 29678899, 2018). "Statistical analysis revealed that increased ZFAS1 expression were correlated with tumor size (p = 0.014), and advanced pathological stage (P=0.001)." (PMID 27246976, 2017). "Next, qPCR assays determined that ZFAS1 expression levels were down-regulated in tumor tissues collected from sh-ZFAS1 group compared with control." (PMID 27246976, 2017). "The expression level of ZFAS1 was determined in collected tumor tissues and adjacent normal tissues by using qRT-PCR." (PMID 29245995, 2017). "Numerous studies reported that the expression levels of ZFAS1 in tumor tissues were dramatically higher than that in adjacent normal tissues." (PMID 29245995, 2017). "ZFAS1 played an important role in tumor biological activities, including cancer growth, proliferation and metastasis." (PMID 28977885, 2017). "Knockdown of ZFAS1 exerted tumor-suppressive functions through reducing cell proliferation and inducing cell apoptosis." (PMID 27246976, 2017). "While another study showed that ZFAS1 transcripts are highly expressed in most HCC tissues compared with the paired non-tumor tissues and the upregulation of ZFAS1 promoted the metastasis through a miR-150 dependent manner." (PMID 27654478, 2016). "MiR-150-5p was already described and experimentally proved to be sponged by ZFAS1 in HCC and associated with tumor invasion and metastasis." (PMID 26506418, 2016). "We also evaluated the correlations between ZFAS1 expression levels in tumor tissues and clinico-pathological features of CRC." (PMID 26506418, 2016). "Furthermore, CRISPR-based genetic screens can systematically identify which ZFAS1-mediated interactions are essential for tumor growth in specific genetic backgrounds." (PMID 41450817, 2026). "Genetic ablation of ZFAS1 profoundly compromised clonogenic potential, evidenced by 68 % reduction in tumor sphere formation capacity, concomitant with downregulation of stemness-associated surface markers (CD133, EPCAM) and activation of caspase-3-dependent apoptotic pathways." (PMID 41450817, 2026). "According to recent research, ZFAS1 plays a tumor‐suppressive role in BC." (PMID 41459628, 2026). "Notably, the upregulation of ZFAS1 has been extensively reported in various malignancies, where it contributes to tumor progression and metastasis." (PMID 40697388, 2025). "Knockdown of lncRNA ZFAS1/ATIC inhibited tumor growth and lung metastasis in vivo." (PMID 39001904, 2024). "Additionally, in vivo research has demonstrated that knockdown of both ATIC and lncRNA ZFAS1 can inhibit tumor growth and lung metastasis." (PMID 39001904, 2024).
tumor (continued). "The current review discusses the mode of action of ZFAS1 in various human cancers and its regulation function related to chemoresistance comprehensively, as well as the potential role of ZFAS1 as an effective and noninvasive cancer-specific biomarker in tumor diagnosis, prognosis, and treatment." (PMID 38856786, 2024). "It was reported that ZFAS1 increased CC tumor growth and cell proliferation by upregulating LIN28." (PMID 35112985, 2022). "The tumor growth model showed that ZFAS1 knockdown significantly inhibited tumor growth (p < 0.05)." (PMID 34980191, 2022). "In addition, in vivo experiment was carried out to explore the function of ZFAS1 in tumor growth of CC." (PMID 35112985, 2022). "A xenograft tumor model was used to explore the oncogenic role of ZFAS1 in vivo." (PMID 35036050, 2022). "Our in vivo experiments showed that silencing of ZFAS1 reduced CC tumor size." (PMID 35112985, 2022). "Besides its role in tumor pathogenesis, ZFAS1 is involved in the molecular cascade leading to a series of diseases, such as osteoarthritis, epilepsy, and atherosclerosis." (PMID 35846429, 2022). "Silencing ZFAS1 significantly inhibited tumor growth (weight and volume) in vivo." (PMID 35036050, 2022). "Recent studies disclosed that miR-135a-5 and miR-150-5p could be used as binding targets of ZFAS1 to participate in the regulation of tumor proliferation, invasion, and migration." (PMID 36514044, 2022). "In addition, we confirmed that ZFAS1 can regulate the autophagy level of NPC cells through the PI3K/AKT pathway through miR-100-3p/ATG10 to affect tumor progression." (PMID 34980191, 2022). "Notably, high ZFAS1 expression in CRC was significantly correlated with tumor size, invasive status (p = 0.0008), and microsatellite stability (p = 0.0077)." (PMID 35036050, 2022). "Accumulating evidence has suggested that ZFAS1 participated in tumor initiation and progression." (PMID 35112985, 2022). "Taken together, ZFAS1 appeared to be involved in the development of tumor metastasis." (PMID 36514044, 2022). "Finally, in vitro assays demonstrated that inhibition of ZFAS1 reduced CC tumor growth and the expression levels of KLF6, but increased the expression levels of miR-190a-3p." (PMID 35112985, 2022). "Therefore, the contribution of ZFAS1/miR-3924 in tumor metastasis via the RHOA/ROCK2 pathway was reported, confirming its potential regulatory effect on RHO GTPase members." (PMID 34771549, 2021). "Moreover, the interactive effects of IMP2, m6A, and ZFAS1 expressions on environmental factors and clinical variables were detected by unconditional logistic regression analysis adjusted for sex, age, tumor size, and tumor differentiation." (PMID 34743750, 2021). "ZFAS1 is upregulated in most tumor tissue, and it may promote the metastasis and development of tumors." (PMID 35198599, 2021). "In addition, the combination of several tumor markers, such as lncRNA ZFAS1, SNHG11, LINC00909, and LINC00654, can improve the accuracy of CRC diagnosis." (PMID 34778084, 2021). "Similar results were obtained from 30 pairs of CRC tissues and matched tumor-adjacent normal tissues, where an elevated expression of ZFAS1 in CRC tissues and a further consistently up-regulated of SNORD12C, SNORD78, and NOP58 were detected by RT-PCR and qPCR assays." (PMID 32443980, 2020). "Consistent with the results in CRC cells, the expression levels of ZFAS1 and NOP58 were elevated in the CRC tissues compared to the levels detected in the tumor-adjacent normal tissues, and a large positive linear correlation pattern was confirmed to exist between ZFAS1 and NOP58 within this cohort." (PMID 32443980, 2020). "In that case, we conducted experiments not only in vitro but also in vivo and found ZFAS1/miR‐296‐5p/USF1 regulation might work as one approach to influence tumour progression." (PMID 31565837, 2019). "Furthermore, in vivo experiment suggested that elevated ZFAS1-exo promoted tumor growth in nude mice." (PMID 31775815, 2019).
tumor (continued). "In addition, we have found that ESCC cells transmitted ZFAS1 to surrounding cancer cells through exosomes and elevated ZFAS1-exo promoted tumor growth in nude mice." (PMID 31775815, 2019). "However, the following studies dramatically indicated its distinct role of cancer promotion, which refuted the tumour suppressor role of ZFAS1." (PMID 31565837, 2019). "ZFAS1 also promotes metastasis by binding miR-150 to abrogate tumor-suppressive function." (PMID 31096997, 2019). "Silenced ZFAS1 or elevated miR-135a suppressed tumor volume and weight of OS in vivo." (PMID 31827400, 2019). "Results showed that AUC was 0.801 (95% CI: 0.724–0.875), suggesting that plasma ZFAS1 could be a promising tumor marker for HCC detection." (PMID 29559565, 2018). "In addition, this meta-analysis revealed that the upregulated expression of ZFAS1 was significantly associated with lymph node metastasis, Tumor Node Metastasis (TNM) stage, and tumor size." (PMID 30544408, 2018). "The human ortholog ZFAS1 has similar features to Zfas1, wherein both are highly expressed in the mammary gland and downregulated in tumors highlighting the potential tumor suppressor gene properties along with their regulatory role in alveolar development and epithelial cell differentiation." (PMID 29732012, 2018). "Thus it can be seen that the prognostic value of ZFAS1 in cancer patients were inconclusive or even contradictory, the role of ZFAS1 as a tumor biomarker for prognosis was unclear." (PMID 28977885, 2017). "Moreover, elevated ZFAS1 expression correlated with tumor size, tumor-node-metastasis (TNM) stage, and lymph node metastasis (LNM)." (PMID 29163829, 2017). "However, several experimental studies have shown that ZFAS1 plays a pivotal role in tumor progression by regulating cell proliferation, invasion, apoptosis, and migration." (PMID 29163829, 2017). "In these studies, ZFAS1 expression in tumor tissues was determined by qRT-PCR." (PMID 29137442, 2017). "Due to insufficient data for other clinicopathological parameters (such as age, distant metastasis, tumor differentiation), the association between ZFAS1 expression and these clinicopathological parameters were not evaluated for the meta-analysis." (PMID 29245995, 2017). "Taken together, ZFAS1 was involved in tumor development and progression and may act as a potential predictive factor for clinical outcomes." (PMID 28977885, 2017). "In addition, analysis of TCGA stomach and normal tissues RNA sequencing data also showed that ZFAS1 expression is up-regulated in tumor tissues compared with normal tissues." (PMID 27246976, 2017). "The pooled analysis demonstrated that elevated ZFAS1 expression correlated with tumor size (> 5 cm vs. < 5 cm; OR = 1.42, 95% CI: 1.03–1.94, P = 0.03), TNM stage (III-IV vs. I-II; OR = 2.31, 95% CI: 1.35–3.95, P = 0.002), and LNM (pos vs. neg; OR = 2.20, 95% CI: 1.15–4.18, P = 0.02)." (PMID 29163829, 2017). "Moreover, our results show that elevated ZFAS1 levels correlate with tumor size, TNM stage, and LNM." (PMID 29163829, 2017). "Knockdown of ZFAS1 in mammary epithelial cells increases their proliferation and differentiation, suggesting that ZFAS1 may serve as a tumor suppressor gene." (PMID 29163829, 2017). "ZFAS1 is a newly identified lncRNA that is downregulated in human breast cancer, which may serve as a tumor suppressor." (PMID 27246976, 2017). "Rescue experiments showed that miR-486 inhibitor could reverse the tumor-suppressing function of ZFAS1 knockdown on MG63 cells." (PMID 29262629, 2017). "MEG3, JPX, RNCR3, and ZFAS1 showed significant decrease with tumour malignant progression." (PMID 29138748, 2017). "To evaluate ZFAS1 deregulation in CRC on expression data reached by different methodical approach we have downloaded and analyzed RNAseq TCGA-dataset COADREAD and confirmed significantly higher levels of ZFAS1 in CRC tumor tissue in comparison to non-tumor colorectal tissue (P < 10−11)." (PMID 26506418, 2016).
tumor (continued). "ZFAS1 was described to function as an oncogene involved in metastatic progression of HCC and authors suggest that this function is associated with ZFAS1 sponging activity on miR-150, which is known to be tumor suppressor in HCC." (PMID 26506418, 2016). "Taken together, the expression of ZFAS1 was significantly increased in GC tumor tissues and plasma, and may decrease after surgery." (PMID 27654478, 2016). "We further investigated whether ZFAS1 is detectable or altered in the tumor and non-tumor paired tissue of independent and larger cohort of CRC patients." (PMID 26506418, 2016). "Accordingly, ZFAS1 may be involved in preventing tumor growth." (PMID 41459628, 2026). "Finally, silencing ZFAS1 significantly repressed tumor formation and metastasis in MTC." (PMID 38946718, 2024). "In addition, ZFAS1 influenced CC tumor growth through miR-190a-3p." (PMID 35112985, 2022). "A recent study on Zfas1 on a tumor-associated nonprotein-coding snoRNA host gene confirmed that three C/D box snoRNAs might regulate the expression of their host gene Zfas1, and further indirectly mediate tumorigenesis." (PMID 31052553, 2019). "Moreover, compared with primary CRC tumours, ZFAS1 was upregulated in metastatic tumours, suggesting ZFAS1 may have a specific role in such cancer metastasis." (PMID 30288832, 2019). "ZFAS1 is a newly identified lncRNA, which might serve as a tumor suppressor." (PMID 31096997, 2019). "ZFAS1 could be used as a predictor for tumor progression in various cancers." (PMID 30544408, 2018). "In addition, the elevated expression of ZFAS1 was correlated with tumor size, TNM stage, and LNM." (PMID 30544408, 2018). "Results of xenograft assay indicated that ZFAS1 knockdown could suppress the tumor growth in vivo." (PMID 29262629, 2017). "Within the tumor microenvironment (TME), exosome-derived ZFAS1 remodels intercellular communication networks, promoting angiogenesis via STAT3/VEGFA signaling, though its immunometabolic regulatory mechanisms warrant further elucidation." (PMID 41450817, 2026). "ZFAS1 robustly promotes HCC cell proliferation and tumor growth by simultaneously deregulating multiple cell cycle and survival pathways through distinct miRNAs." (PMID 41450817, 2026). "Among the lncRNAs, ZFAS1 and WDFY3-AS1 are tumor suppressor lncRNAs while lnc00205 is an oncogenic miRNA." (PMID 37737288, 2023). "Previous studies have noted that lncRNA ZFAS1, lncRNA HOXA11-AS, and linc00261 can be used as novel tumor markers for GC screening." (PMID 37291405, 2023). "Based on this evaluation, LINC00877, SLC25A5-AS1, ILF3-DT, LRRC75A-AS1, LINC00324, CD27-AS1, ZFAS1, SNHG5, MIR762HG, and SNRK-AS1 were the top significantly downregulated tumor suppressor candidates in MCL cases." (PMID 36359790, 2022). "ZFAS1 is used as an oncogenic lncRNA, which can promote NPC cell proliferation, migration and tumor growth." (PMID 34980191, 2022). "In this study, we found that ZFAS1 expression was remarkably upregulated in CRC tissues and was positively correlated with advanced pathological stages and larger tumor sizes." (PMID 35036050, 2022). "Taken together, the lncRNAs in common (EBLN3P, AC004542.2, ZFAS1, and GAS5) seemed the most potentially predictive or prognostic genes for PCa that were closely related to the tumor progression." (PMID 36514044, 2022). "The expression levels of ZFAS1 and KLF6 were both significantly elevated, while the expression of miR-190a-3p was inhibited in CC tumor tissues." (PMID 35112985, 2022). "The previous study revealed that ZFAS1 acted as an oncogene in HCC progression by binding miR-150 and abrogating its tumor-suppressive function." (PMID 35386284, 2022). "The results showed that AC005261.1, LINC01578, ZFAS1, EBLN3P, THUMPD3-AS1 and GAS5 were highly expressed in tumor than adjacent normal samples." (PMID 36514044, 2022).
tumor (continued). "Expression analyses from the other two independent datasets (GSE29079, GSE94767) showed four (AC004542.2, ZFAS1, EBLN3P, GAS5) out of nine lncRNAs were significantly overexpressed in tumor." (PMID 36514044, 2022). "Here, we found that the expression levels of ZFAS1 and KLF6 were elevated, while the expression of miR-190a-3p was inhibited in CC tumor tissues." (PMID 35112985, 2022). "The levels of ZFAS1, miR-497-5p and HMGA2 in the excised tumour sections were measured after 35 days." (PMID 34552050, 2021). "Collectively, in vivo experiments demonstrated that IMP2 knockdown inhibits the tumor growth and prognosis of the xenografts via the interaction of IMP2 with the ZFAS1/OLA1 axis through m6A-induced stability in CRC." (PMID 34743750, 2021). "OLA1 is also highly expressed in various tumor types including CRC, and the expressions of OLA1 and ZFAS1 in CRC tissues are highly consistent." (PMID 34743750, 2021). "To date, studies have focused on the recognition of tumor-promoting lncRNAs such as HOXC13-AS and ZFAS1, and further studies can identify tumor-suppressing lncRNAs regulating the miRNA/PTEN axis." (PMID 33670518, 2021). "The ZFAS1 gene is frequently amplified in HCC, which promotes metastasis through sponging tumor-suppressive miR-150 and then activating ZEB1 (zinc finger E-box-binding homeobox 1), MMP14 (matrix metallopeptidase 14), and MMP16." (PMID 34072570, 2021). "All these results suggest that miR‐1271‐5p acts as a tumor inhibitor in LAD, and miR‐1271‐5p regulates LAD development by interacting with lncRNA ZFAS1." (PMID 32515146, 2020). "The results imply that miR‐1271‐5p functions as a tumor suppressor in LAD, and lncRNA ZFAS1 promotes LAD development by downregulating miR‐1271‐5p." (PMID 32515146, 2020). "In the top 10 altered couples for these tumor types, 9 are identical: SNORA13/EBP41L4A-AS1, SNORA27/RPL21, SNORA31/TPT1, SNORA71E/SNHG11, SNORA72/RPL30, SNORD102/RPL21, SNORD12/ZFAS1, SNORD12B/ZFAS1, and SNORD12C/ZFAS1." (PMID 32046192, 2020). "MiR‐1271‐5p functioned as a tumor suppressor in LAD, and lncRNA ZFAS1 promoted LAD development by downregulating miR‐1271‐5p." (PMID 32515146, 2020). "In summary, our data demonstrated the overexpression of ZFAS1 in PAAD and its clinical correlations with tumour grade and prognosis." (PMID 32550827, 2020). "Considering that ZFAS1 still showed a degree of expression in normal pancreatic tissue and the effects on the ZFAS1 expression level caused by multiple factors (sex, tumour grade and drinking habits), ZFAS1 may not be valuable for the diagnosis of PAAD currently." (PMID 32550827, 2020). "Amplified expression ZFAS1 in EOC tissues was positively correlated with advanced clinical stage, larger tumour size, and lymph‐node metastasis." (PMID 30288832, 2019). "The effects of ZFAS1, miR‐296‐5p and USF1 on tumour growth were further confirmed using xenograft model." (PMID 31565837, 2019). "Published studies indicated that ZFAS1 directly repressed KLF2 and NKD2 expression to promote tumor cell proliferation, and induced ZEB1 to enhance the epithelial–mesenchymal transition (EMT) and metastatic ability." (PMID 29678899, 2018). "Our data demonstrated that SP1-induced ZFAS1 contributed to CRC progression by upregulating VEGFA via competitively binding to miR-150-5p, which acts as a tumor suppressor by targeting VEGFA in CRC." (PMID 30250022, 2018). "The abundance of ZFAS1 expressed in CRC was found to correlate with lymphatic invasion, TNM stage, tumor invasion and metastasis." (PMID 28108736, 2017). "The data showed that ZFAS1 was highly expressed in GC cell lines (AGS, SGC7901 and BGC-823) compared in non-tumor gastric cell line GES-1." (PMID 27654478, 2016). "Similarly, LncRNA ZFAS1, a known oncogenic molecule of CRC, is involved in tumorigenesis by targeting miR-484, however miR-484 overexpression reversed the tumor enhancing effect of ZFAS1 on CRC cells." (PMID 35356223, 2022).